LDHAP5 (lactate dehydrogenase A pseudogene 5)
Synonyms: formerly LDHAL5
Gene: Processed pseudogene on chromosome 10 (118,932,674 to 118,933,295, reverse strand). Ensembl gene ENSG00000213574.
Diseases named in the same sentence as LDHAP5 in open-access papers:
LDHAP5 is named in the same sentence as 4 diseases in open-access papers, as found by Europe PMC text mining. Sharing a sentence is not in itself a finding about the gene and the disease. The quoted sentences say what the papers report.
ovarian carcinoma (1 paper, 2020). A malignant neoplasm originating from the surface ovarian epithelium. "To further confirm the role of the LDHAP5 pseudogene at the in vivo and in vitro level, we need to construct ovarian cancer cell lines that differentially express LDHAP5, with clinical pathological specimens from ovarian cancer patients also used to verify our findings." (PMID 32536817, 2020).
ovarian serous cystadenocarcinoma (1 paper, 2020). A malignant serous cystic epithelial neoplasm arising from the ovary. "LDHAP5 was associated with the occurrence and prognosis of ovarian serous cystadenocarcinoma, and thus shows potential as a novel therapeutic target against such cancer." (PMID 32536817, 2020). "Among the 63 up-regulated pseudogenes identified, LDHAP5 demonstrated the greatest potential as a candidate pseudogene due to its significant association with poor overall survival in ovarian serous cystadenocarcinoma." (PMID 32536817, 2020). "Pearson correlation analysis showed that EGFR (R = 0.16, P = 0.00072), PTEN (R = 0.098, P = 0.043), SIRT1 (R = 0.094, P = 0.013), RELA (R = 0.18, P = 0.00013) and CREB1 (R = 0.16, P = 0.00094) were significantly correlated with LDHAP5 expression in ovarian serous cystadenocarcinoma." (PMID 32536817, 2020). "Further analysis revealed that EGFR was the potential target mRNA of LDHAP5, which may play an important role in ovarian serous cystadenocarcinoma." (PMID 32536817, 2020).
cancer (2 papers, 2020 to 2021). A tumor composed of atypical neoplastic, often pleomorphic cells that invade other tissues. "KEGG pathway analysis revealed that LDHAP5 showed significant enrichment in MicroRNAs in cancer, Pathway in cancer and PI3K-AKT signaling pathway." (PMID 32536817, 2020).
LDHAP5 also shares sentences with these, for which no sentence is quoted: uterine corpus endometrioid carcinoma (1 paper).